MIR200C (microRNA 200c)
Synonyms: hsa-mir-200c; MIRN200C; mir-200c
Gene: MicroRNA gene on chromosome 12 (6,963,699 to 6,963,766, forward strand). Ensembl gene ENSG00000207713.
Pathways (Reactome):
Cell-Cell communication: Regulation of CDH11 mRNA translation by microRNAs
Immune System: Regulation of PD-L1(CD274) translation
Signal Transduction: Pre-NOTCH Transcription and Translation
Gene Ontology:
Biological process: miRNA-mediated post-transcriptional gene silencing
Cellular component: RISC complex
Homologues: Orthologues: chimpanzee MIR200C (100% identical), mouse Mir200c (97% identical), rabbit MIR200C (97% identical), guinea pig MIR200C (87% identical), rat Mir3575 (59% identical). Paralogues in human: MIR200B (63% identical), MIR200A (56% identical).
Diseases named in the same sentence as MIR200C in open-access papers:
MIR200C is named in the same sentence as 3 diseases in open-access papers, as found by Europe PMC text mining. Sharing a sentence is not in itself a finding about the gene and the disease. The quoted sentences say what the papers report.
cholestasis (1 paper, 2022). Impairment of the bile flow caused by obstruction within the liver, or outside the liver in the bile duct system. "On a molecular level, the pro-proliferative IL-6/AKT feedback loop was activated in Mir200c−/− livers but was inhibited in Sesn1−/− livers upon cholestasis in mice." (PMID 34880414, 2022).
cancer (2 papers, 2017 to 2020). A tumor composed of atypical neoplastic, often pleomorphic cells that invade other tissues. "GRHL2 upregulates expression of the MIR141, MIR200A, MIR200B, MIR200C and MIR429 microRNAs by binding to their regulatory elements in a number of cancers." (PMID 32005677, 2020).
tumor (1 paper, 2018). "To distinguish the specific roles of the miR-200c and miR-141 families, we infected RT2_DKO tumor-derived cells with adenoviruses harboring either the endogenous Mir141~200c locus (ad-141~200c) or the Mir141 or Mir200c genes alone (ad-141 and ad-200c, respectively)." (PMID 30405106, 2018).